CDK4 (cyclin dependent kinase 4)
Diseases named in the same sentence as CDK4 in open-access papers (continued):
Sharing a sentence is not in itself a finding about the gene and the disease.
tumor (continued). "The tumor growth curve showed that anti-CD8 antibody was sufficient to increase tumor growth of Cdk4−/− similar to WT cancer cells." (PMID 37833461, 2023). "Further studies have proved that the tumor suppressor effect of miR-193b occurs through diminishing CCND1, a cell cycle regulator associated with cyclin-dependent kinase 4 or 6 (CDK4/6)." (PMID 37007040, 2023). "Such a cytostatic effect is expected to lead to tumor growth stabilization; however, tumor shrinkage was also reported in CDK4/6i monotherapy trials, suggesting additional cellular effects." (PMID 37835528, 2023). "The INK4 family is a set of intrinsic tumor suppressor factors that competitively bind to CDK4/6, preventing the formation of the cyclin D–CDK4/6 complex, hence inhibiting cell cycle progression." (PMID 37835528, 2023). "Given that the presence of ER correlates with an upregulation of AR’s tumor suppressor function, trial NCT05065411 will target CDK4/6 to inhibit cell growth and proliferation while modulating AR’s activity to induce tumor suppression." (PMID 38067367, 2023). "The addition of CDK4/6 inhibitors to endocrine therapy increases therapeutic benefit in ER+ tumours and is now a commonly used treatment." (PMID 37543694, 2023). "In the same vein, understanding of mechanisms of tumor resistance to CDK4/6-inhibitor therapy will help guide choice for further treatment lines." (PMID 37760527, 2023). "Pathological examination showed coagulation necrosis in the chest wall tumor, but immunohistochemical staining revealed murine double minute 2- and Cyclin-dependent kinase 4-positive cells with irregular nuclear size and bizarre morphology." (PMID 36788154, 2023). "Our large collection of cell lines from different tumor histotypes further completes previous works on the evaluation of CDK4/6i." (PMID 37964967, 2023). "Different murine models investigated the influence of CDK4/6 inhibition on tumor-infiltrating immune cells." (PMID 36817127, 2023). "With the increased use of CDK4/6 inhibitors in combination with aromatase inhibitors in early-stage BC, patients with advanced BC are more likely to have tumours that have progressed following treatment with a CDK4/6 inhibitor." (PMID 37543694, 2023). "ETH-155008 further blocks tumor cells in the G1 phase, to some extent avoiding the development of CDK4/6 inhibitor resistance via a synergistic effect." (PMID 38138549, 2023). "As the ER pathway is known to evade through the Cylin D-CDK4/6-Rb pathway to promote tumor growth or proliferation, inhibition of CDK4/6 contributes to aromatase inhibition." (PMID 36985460, 2023). "The work suggests that DNA damage induced by either Cdk4 or Cdk6 knockout triggers anti-tumor immune responses through the STING-dependent type I interferon response." (PMID 37833461, 2023). "These agents have demonstrated encouraging anti-tumor activity in early phase trials which have included patients treated previously with a CDK4/6 inhibitor." (PMID 37035239, 2023). "CDK4/6 inhibitors prevent the G1/S transition of the HR + tumour cell cycle and block the downstream pathway that ultimately leads to the activation of E2F transcription factors, promoting DNA replication and progression through the S phase." (PMID 37189701, 2023). "Here, we found that pharmacologic inhibition of CDK4/6 or deletion of CDK4 in tumor cells inhibited tumor growth only in the immunocompetent mice but not in the immunodeficient mice." (PMID 37833461, 2023). "We have provided evidence that either Cdk4 or Cdk6 knockout triggers DNA damage of cancer cells and retards tumor growth in vivo through activation of STING-dependent type I interferon induction pathway and anti-tumor immune responses." (PMID 37833461, 2023). "This establishes PI3K, AKT or mTORC1/2 signalling plays an important role in tumour progression in the context of CDK4/6 inhibitor treatment." (PMID 37543694, 2023).
tumor (continued). "We investigated genomic and transcriptomic differences between the MKShi/ERSlo subgroup and other ER+/HER2− tumours and examined markers that have been reported to predict benefit from CDK4/6i and immune checkpoint inhibitors (ICI)." (PMID 37935787, 2023). "These diverse roles of CDK4/6 in tumor progression underscore their potential as targets in cancer therapy." (PMID 38138549, 2023). "Since the strongest elevation of the antigen-processing machinery at the level of gene expression was observed in CDK4/6-sensitive cell lines, these responses appear to be at least partially tumor-intrinsic." (PMID 36768557, 2023). "Treatment with CDK4/6 inhibitors exerts direct effects on T lymphocyte function in the tumor microenvironment (TME), including a decrease in the proliferative capacity of regulatory T cells and an increase in the activity of effector T cells." (PMID 38023235, 2023). "The results showed that tumor bearing Cdk4−/− cells were much smaller than those bearing control cells." (PMID 37833461, 2023). "For example, CCL5 (Chemokine (C-C motif) ligand 5) secreted by Aurora kinase A (AURKA) or CDK4/6 inhibitor-induced melanoma senescent cells promotes the recruitment of tumor-infiltrating leukocytes (TILs), enhancing their killing effect on tumor cells." (PMID 37174106, 2023). "As CDK4 is a readily druggable target, we were able to show that CDK4 up-regulation contributed functionally to recurrent tumor growth, as blocking CDK4 enhanced CT-179 efficacy." (PMID 37333134, 2023). "Here, we report a STING-dependent anti-tumor immune mechanism responsible for tumor suppression by CDK4/6 blockade." (PMID 37833461, 2023). "An RB-proficient transgenic animal model of tumour served as the basis for the initial research, indicating a connection between CDK4/6 regulation and the immune system." (PMID 36768557, 2023). "The tumor-suppressive efficacy of high-dose testosterone was mediated by the important role of the Rb/p130-E2F complex and strengthened by CDK4/6 inhibitor treatment." (PMID 37142586, 2023). "Combination therapy of CDK4/6 inhibitors with immune checkpoint blockade has been shown to increase anti-tumor efficacy in preclinical models and provides the rationale to evaluate this combination clinically." (PMID 37035239, 2023). "The main mechanisms of its anti-tumor effects are identified as: (i) a selective inhibition of cyclin-dependent kinase 4 (CDK4), which regulates the G0/S and G1/S checkpoint of the cell cycle." (PMID 37103365, 2023). "Another study supported that CDK4/6i remarkably strengthened tumor immunogenicity and provided a theoretical basis for combination therapy with CDK4/6 inhibitors and immunotherapies as anticancer treatments." (PMID 38037159, 2023). "Mechanistically, our results showed that Cdk4 and Cdk6 deficiency induced DNA damage, which activated STING-dependent Type I IFN response and anti-tumor immunity." (PMID 37833461, 2023). "Inhibition of the type‐1 TGFβ receptor (TGFβ‐R1) kinase in combination with CDK4/6 decreased cell invasion and inhibited tumor growth in cell line models." (PMID 37840530, 2023). "Of note, CDK4/6 inhibitors regulate PD-L1 stability in tumor cells, augment cytotoxic T cell activation, and attenuate suppressive functions of regulatory T cells, all of which contribute to robust antitumor immunity with reinforced host immune surveillance." (PMID 36635767, 2023). "Our current study provided novel insights into the mechanisms underlying ER+ BC drug resistance and demonstrated that PFKFB4 plays an essential role during tumour cell stemness transformation and acquired CDK4/6 inhibitor resistance." (PMID 36127291, 2023). "Current therapies based on MEK, BRAF and CDK4/6 inhibitors tend to induce resistance by activating OXPHOS and fatty acid oxidation, thus reducing the tumour mass but increasing the risk of relapse." (PMID 37495601, 2023).
tumor (continued). "On one hand, CDKN2A is a critical tumor suppressor that induces cell cycle arrest by inhibiting the CDK4/6-Cyclin D complex upon activation." (PMID 37665670, 2023). "Surprisingly, translational results from these ongoing studies have shown that CDK4/6 inhibitors play a number of crucial functions, such as cross talk between tumor cells and the host immune system." (PMID 36768557, 2023). "Despite being optional in normal cells, CDK4/6 have been proven to be essential for the growth of tumour cells in knockout experiments." (PMID 36768557, 2023). "In general, SHCBP1 can promote tumor growth and invasion in GC by regulating the CDK4-cyclin D1 cascade and caspase-3 and caspase-PARP-dependent apoptosis pathways." (PMID 36920183, 2023). "Previous study has shown that selective inhibitors of CDK4/6 induce tumor cell cycle arrest and promote anti-tumor immunity." (PMID 36739402, 2023). "Recent studies uncovered novel therapeutic potentials for CDK4/6i, suggesting an immunomodulatory effect that goes beyond the intrinsic anti-tumor properties related to cell cycle inhibition." (PMID 37509319, 2023). "Future studies including patients treated with T-DXd after tumor progression to ET + CDK4/6i will clarify this point." (PMID 37069173, 2023). "In general, CDK4/6 inhibitors enhance the anti-tumor immune response by promoting antigen processing and presentation, stimulating DC maturation, and reducing the population of immunosuppressive Tregs." (PMID 37345111, 2023). "We sought to identify radiomic features associated with RECIST response and OS in ER + /HER2- MBC patients treated with CDK4/6i by interrogating the tumor and tumor microenvironment on CT imaging." (PMID 37567880, 2023). "Treatment with GSK3326595 significantly diminished tumor growth in the mice, accompanied by decreased H4R3me2s and downregulation of CDK4/6 in the drug-treated tumors." (PMID 36797243, 2023). "The analysis of the cfDNA NGS panel before treatment with larotrectinib revealed both TPM3::NTRK1 fusion and MDM2/CDK4 amplification, reliably reflecting the genetic alterations of the original pelvic tumor tissue." (PMID 36652666, 2023). "The combination of fulvestrant, palbociclib and capiversertib (an inhibitor of AKT1, AKT2 and AKT3) has been shown to be effective in suppressing tumor growth in preclinical models that were dually resistant to ET and CDK4/6 inhibitors." (PMID 37035239, 2023). "Greater nuclear NFAT expression and enhanced transcriptional activity driven by CDK4/6 inhibition altered the cytokine setting in the tumour microenvironment and promoted the activation of effector T cells." (PMID 36768557, 2023). "In some mouse tumor models with specific genetic backgrounds, the loss of CDK4 and CDK6 impedes tumor progression." (PMID 37958642, 2023). "Among them, we focused on CDC25A and CDK4, which were involved in tumor growth and radiosensitivity." (PMID 37173384, 2023). "Here we observed the synergistically anti-tumor effects of SCR-6852 in combination with a CDK4/6 inhibitor, Palbociclib." (PMID 37580832, 2023). "In tumor cells, CDK4/6 hyperactivation results in genomic and chromosomal instability with uncontrolled cell proliferation, which ultimately leads to abnormal cell cycle regulation." (PMID 35707364, 2022). "Compared with the control group and the abemaciclib group, LPM3770277 treatment significantly reduced the expression of CDK4/6 protein in the tumor tissue." (PMID 35479314, 2022). "The interaction of CDK4/6 to cyclin D1 leads to phosphorylation of the Rb protein, providing the initiating signal for tumor cell proliferation." (PMID 36595763, 2022).
tumor (continued). "In our recent report, we verified the strong synergistic tumor inhibition of pyrotinib (a novel small-molecule tyrosine kinase inhibitor mainly targeting HER2) combined with CDK4/6 inhibitor in HER2-positive GC patients." (PMID 36463209, 2022). "The tumor suppressor, Rb interacts with E2F transcription factor to regulate cell cycle, and Rb is initially phosphorylated by CDK4/6 signaling." (PMID 35814226, 2022). "A tissue microarray analysis of 109 primary tumour biopsies revealed a subset of patients (20–23%) with intact Rb, but defective p16 or overexpression of CDK4 and/or CDK6." (PMID 34921235, 2022). "Preclinical studies have reported that increased levels of cyclin D1 and CDK4 confer resistance to HER2-inhibitors in tumor cells, and CDK4/6 inhibitor can regain the sensitivity to HER2-directed agents." (PMID 35321427, 2022). "Despite significant research efforts, tumor heterogeneity and difficulties distinguishing endocrine resistance from CDK4/6 inhibitor resistance have impeded predictive biomarker discovery." (PMID 36176758, 2022). "Numerous CDK4/6 inhibitors potently suppress the proliferation of Foxp3 + regulatory T cells (TReg) in the tumor microenvironment (TME), which is likely an RB-dependent phenomenon." (PMID 35248122, 2022). "Taken together, our data demonstrate that FAK inhibition blocks tumor proliferation by inducing G1 arrest, in part through decreased CDK4/6 protein stability by nuclear FAK." (PMID 35525274, 2022). "However, in addition to this, continual CDK4/6 inhibitor dosing could also induce genotoxic damage if this dose causes cell cycle delays instead of a complete G1 arrest, as we observed in a range of tumour types that cannot be fully arrested by palbociclib." (PMID 35037284, 2022). "The combination of a CDK4/6 inhibitor and PD-1 antibody significantly inhibited tumor cell growth and improved survival in carcinomatous mice." (PMID 35884537, 2022). "In conclusion, the current study demonstrated that sequential abemaciclib treatment following eribulin enhanced anti-tumor activity in vitro and in vivo on the CDK4/6 inhibitor-resistant cells by more effectively inhibiting the G2/M cell cycle phase." (PMID 35008374, 2022). "To determine if FAK inhibition reduced CDK4/6 expression in vivo, we analyzed tumor lysates via immunoblotting." (PMID 35525274, 2022). "This dual targeting compound displayed better anti-tumor efficacy than PARPi or CDK4/6i alone and in combination." (PMID 35270034, 2022). "CdK4/6i have been reported to increase tumor immunogenicity by overcoming two principal mechanisms of tumor immune evasion." (PMID 36741710, 2022). "Of the primary tumour biopsies, 22.7% of the tumours were positive for both Rb and CDK4, 52.9% were positive for Rb and CDK6, and 43.1% was positive for Rb, and CDK4 or CDK6." (PMID 34921235, 2022). "Recently, it has been reported that CDK4/6i can also induce metabolic stress in tumor cells, leading to expression of chemokines such as CCL5 and CXCL10 that can further enhance anti-tumor immune responses." (PMID 35248122, 2022). "The CDK4/6 inhibitor-resistant tumor was then engrafted into a cohort of NOD/SCID mice to generate the CDK4/6 inhibitor-resistant model." (PMID 35664774, 2022). "Increased levels of chemokines such as CXCL9 and CXCL10 from CDK4/6 inhibition also drive T cell tumor infiltration." (PMID 35911672, 2022). "In vivo, co-targeting FGFR4 and CDK4/6 also showed marked inhibition of tumor growth than single agent treatment." (PMID 35463335, 2022). "Again, also during the development of endocrine resistance, a functioning Rb protein can still be available, making the tumor potentially sensitive to the mechanism of inhibition done by CDK4/6i." (PMID 35330128, 2022). "Based on these positive findings, we investigated the anti-tumor activity of the combination of CDK4/6 inhibitors with lenvatinib in a panel of HCC cell lines." (PMID 35936714, 2022).
tumor (continued). "As expected, CDK4 played an oncogenic role in PCa as its higher expression predicted higher GS and tumor stage, and a worse outcome." (PMID 35350771, 2022). "CDK4/6 interacts with the D-type cyclins (cyclin D), forming functional complexes that phosphorylate the retinoblastoma (RB) tumor-suppressor gene product." (PMID 36005200, 2022). "In CM, the combination of MEKi plus CDK4/6i reduces tumor growth in vitro and in vivo, across genomic subtypes, and in BRAFi/MEKi-resistant patient-derived xenografts." (PMID 35513054, 2022). "CDK4/6 inhibitors contribute to G0/G1 phase cell cycle arrest by preventing the phosphorylation of pRb which leads to the inhibition of tumor progression in a variety of cancers." (PMID 35053461, 2022). "Overexpression of CDK4/6 leads to the activation of the anti-aging mechanism of tumor cells and promotes the formation of tumors." (PMID 36144542, 2022). "First, selective CDK4/6 inhibitors promote anti-tumor immunity by increasing type III interferon production and enhancing tumor antigen presentation." (PMID 35884366, 2022). "In this sense, preclinical studies revealed that resistant tumor cells exhibited augmented levels of cyclin D1 and CDK4, and the subsequent addition of a CDK4/6 inhibitor restored cell sensitivity to HER2-targeted therapies." (PMID 36139701, 2022). "In line with this, the expressions of cyclin D1 and cycle-dependent kinase CDK4 were also significantly downregulated with licoricidin treatment, which promotes the exit of tumor cells from cell cycle and inhibition of cancer proliferation." (PMID 36339587, 2022). "The role that CDK4 plays in cancer and the development and utility of CDK4/6-targeted therapies in various tumor types are discussed in greater detail in the remainder of this article." (PMID 36051751, 2022). "CDK4 amplification and Rb expression were closely monitored in this population of advanced tumor patients." (PMID 35884441, 2022). "Because metabolic pathways are often subverted in tumor cells, the roles that CDK4 and CDK6 play in malignant cell metabolism as it relates to cell survival is an active area of research." (PMID 36051751, 2022). "Together these recent findings suggest that shorter intervals of CDK4/6i treatment would, at a minimum, be sufficient to improve the anti-tumor T cell phenotype, and maintain a favorable distribution of effector/regulatory T cell subsets within tumors." (PMID 35444175, 2022). "Treatment with GLR2007 inhibited cell proliferation to an extent equivalent to or greater than CDK4/6 inhibitor abemaciclib in 77 (89.5%) of the 86 mammalian tumor cell lines tested." (PMID 36033522, 2022). "Recently, researchers recognized that tumor regression mediated by CDK4/6 inhibition is partially dependent on the presence of cytotoxic T cells." (PMID 35756622, 2022). "The authors correlated the stunting of tumor growth with the antagonizing role of palbociclib in DUB3-driven CDK4/6 activation, consequently preventing EMT and metastases." (PMID 35681689, 2022). "These palbociclib-resistant models were sensitized to MEK inhibitors, showing dependency on the active MAPK signaling pathway for tumor development when CDK4/6 was inhibited." (PMID 35892870, 2022). "Inhibition of CDK4/6 enhances tumor antigen presentation and effector T cell infiltration and activation, and it markedly suppresses the proliferation of regulatory T cells." (PMID 35360875, 2022). "Western blot analysis showed that the expression of Cyclin D1 and CDK4 in tumor xenograft was inhibited by knockdown of NDUFA4." (PMID 35977935, 2022). "In both tamoxifen–resistant ER+ MCF7 xenografts and palbociclib–resistant ER+ MCF7 xenografts, significant tumor suppression was achieved with a combination of CDK4/6 inhibitors and DHT." (PMID 36556209, 2022). "Numerous preclinical studies have reported that CDK4/6i can boost anti-tumor immune responses in models of breast and other cancers." (PMID 35248122, 2022).